EGFR (epidermal growth factor receptor)
Diseases named in the same sentence as EGFR in open-access papers (continued):
Sharing a sentence is not in itself a finding about the gene and the disease.
tumor (continued). "Furthermore, the differences of H3K36me3 cfChIP enrichment in EGFR‐WT and EGFR‐mutant tumours reveal of cfChIP‐seq can be used to study gene expression patterns in NSCLC tumours of different molecular subtypes." (PMID 36825535, 2023). "Similarly, a randomized phase II trial of seribantumab in combination with erlotinib in patients with EGFR wild-NSCLC demonstrated progression-free survival benefits in patients with detectable HRG mRNA in the tumor." (PMID 37947595, 2023). "Likewise, a bacteriophage Φ29 RNA has been engineered to incorporate cholesterol-conjugated EGFR RNA aptamer and used to decorate EVs carrying siR as a targeted anti-tumour treatment." (PMID 37189850, 2023). "This tumor also had a mild correlation between EGFR and CD8+ T cells and dendritic cells." (PMID 37370859, 2023). "Moreover, treatment with the anti-EGFR immunolipoplexes containing IL-12/ILSal, and doxorubicin significantly reduced tumor growth (p < 0.001)." (PMID 37612696, 2023). "Cancer cells that underwent EGFR/PARPi treatment or control cells were retransplanted into a new cohort of mice, and defined numbers of cancer cells were observed for the assessment of tumour growth inhibition in the presence of different antibodies." (PMID 37441599, 2023). "Furthermore, the loss of RUNX1 affects the expression of EGFR and STAT3, thereby regulating the downstream pathways and ultimately regulating the function of tumor cells." (PMID 37760803, 2023). "Epidermal growth factor receptor (EGFR) belongs to a family of cell surface receptor tyrosine kinases whose wild-type signaling contributes to the proliferation of tumor cells, evades apoptosis, and promotes tumor proliferation and invasion." (PMID 36770689, 2023). "Additionally, epidermal growth factor receptor (EGFR) plays pivotal role in tumour growth and angiogenesis." (PMID 37165800, 2023). "High expression of CD147 is associated with tumor invasion and metastasis and it forms complexes with CD44 and EGFR in the LRMs, promoting invasiveness in breast epithelial cells through the hyaluronan-CD44-dependent EGFR-Ras ERK signaling pathway." (PMID 37648771, 2023). "EGFR staining was significantly associated (Fisher’s exact test p = 0.001) with tumor histotype; interestingly, EGFR MM stained only 6/265 HGSOC cases compared to 7/45 non-HGSOC cases." (PMID 37041632, 2023). "Similarly, we found that rAAV‐miRNA133b transgene expression was enhanced not only in tumour tissues, but also in EGFR‐positive tissues including liver and kidney." (PMID 37469226, 2023). "Secondly, advanced NSCLCm+ may exhibit different tumor-biological behavior compared to NSCLCm+ in a locally advanced stage, potentially rendering tumor cells in the advanced stage more sensitive to EGFR-TKIs32." (PMID 37537219, 2023). "Vaccination decreased tumor burden after induction of the EGFR transgene." (PMID 36875137, 2023). "This interaction may influence the downstream signaling of EGFR and impact tumor growth and resistance to therapy." (PMID 38003512, 2023). "Although anoikis is mediated by multiple signaling pathways such as the Integrin-FAK, PI3K/Akt and MAPK pathways 23, 37, 38, studies have highlighted the crucial role of the EGFR pathway in conferring anoikis resistance to tumor cells in peripheral blood and facilitating metastasis 39-43." (PMID 37928267, 2023). "YTHDF1 increased the translation of EGFR mRNA via binding to m6 A sites in the 3′-UTR of the EGFR transcript, thus leading to the aberrant activity of downstream signal pathways that could promote tumor progression." (PMID 36835633, 2023).
tumor (continued). "The TME generalization may change with the progression of the tumor, and therefore, resistance to EGFR-TKI may enhance the response to immunotherapy response." (PMID 37266427, 2023). "The low levels of immune suppressive tumor microenvironment mediated by EGFR inhibitor treatment may create a window of opportunity, in which vaccination can more effectively generate anti-tumor immunity for secondary prevention." (PMID 36875137, 2023). "Therefore, the EGFR assay in this study yielded much lower sensitivity in order to detect only high EGFR expressors, typically EGFR amplified tumour cells." (PMID 37568909, 2023). "Besides, PD-L1 has been shown to exert immune-independent tumorigenicity on a variety of tumor cell types, and interact with key molecules in tumor progression such as EGFR." (PMID 36802389, 2023). "In order to accomplish a multidrug combination therapy, a nano antibody that targets the inhibition of the EGFR (epidermal growth factor receptor), one of the tumor indicators, was mixed with the platinum-based medication 56MESS and intercalated into a tetrahedron DNA origami." (PMID 37111997, 2023). "In particular, the anti-PD-L1 antibody-induced increase in EVs from mutant EGFR cells could have broad ranging effects on the tumor microenvironment and tumor immune landscape that could contribute to resistance to immunotherapy." (PMID 36915197, 2023). "In addition, miRNA133b expression was found to significantly inhibit tumour growth and EGFR expression, and the luciferase transgene expression significantly elevated after ss‐rAAV‐Fluc‐miRNA133b vector transduction compared with the ss‐rAAV2‐Fluc vector." (PMID 37469226, 2023). "The EGFR pathway can be activated to cause VEGF production and VEGFR activity, to promote angiogenesis through upregulation of hypoxia-dependent HIF-α expression, while the EFGR-TKIs directly suppresses tumor growth via preventing the EGFR pathway, and block the VEGF to inhibit angiogenesis." (PMID 37316870, 2023). "Indeed, GBM tumor cells treated with EGFR CAR-T cells soon acquired resistance to treatment and relapsed due to the upregulation of immuno-suppressive genes, including inhibitory immune checkpoints." (PMID 37046597, 2023). "Subsequently, tumor cells along with stromal cells generate various growth factors represented by epidermal growth factor receptor (EGFR) and insulin-like growth factor 1 (IGF-1) via autocrine and paracrine pathways to stimulate the continuous proliferation of cancer cells." (PMID 38067347, 2023). "Moreover, monoclonal antibody-based therapies have been developed, targeting specific receptors in tumor cells, such as EGFR, VEGF, or PD-L1, to impede tumor growth." (PMID 37836749, 2023). "EGFR monoclonal antibodies (EGFRMAb), such as panitumumab and cetuximab, could inhibit tumor cell growth." (PMID 36058633, 2023). "In addition, in this tumor, the authors observed a high correlation between EGFR and MET (Rho = 0.698, p = 2.31 × 10−26)." (PMID 37370859, 2023). "Finally, the anti-EGFR antibody panitumumab was coupled to IRDye700DX and investigated in a postsurgical setting to remove microscopic tumor remnants." (PMID 36839652, 2023). "Heavily pre-treated EGFR-TKI-advanced EGFR-mutant NSCLCs with high expression of PD-L1 (≥25% of tumor cells) had a better median OS (mOS) than that with low expression of PD-L1 (<25% of tumor cells) (13.3 vs. 9.9 months) after ICI therapy in a Phase II ATLANTIC study." (PMID 38001917, 2023).
tumor (continued). "Notably, a compelling correlation is observed between TNBC tumor cells and the basal-like subtype, as evidenced by their shared high expression of the epidermal growth factor receptor (EGFR) and the keratin family members KRT5, KRT17, and KRT14." (PMID 37627192, 2023). "Considering that besides the MAPK pathway, multiple oncogenic drivers such as EGFR or the androgen receptor promote fatty acid synthesis, the here proposed combinatorial treatment may be applicable to several tumor types." (PMID 37072838, 2023). "In addition, BBR was reported to inhibit tumor cell growth through suppression of phosphorylation of EGFR and other signaling mediators such as ERBB2 and VEGF." (PMID 37170144, 2023). "Alternatively, another study showed that loss of the intestinal desmosomal cadherin resulted in decreased epithelial cell proliferation and suppressed xenograft tumor growth in mice, interfering downstream with the epidermal growth factor receptor (EGFR) transduction." (PMID 38203664, 2023). "AnxA6 acts as a tumor suppressor through inhibiting EGFR/ERK pathway, therefore we would explore whether SUMOylation of AnxA6 is involved in EGFR/ERK signaling regulation." (PMID 37528485, 2023). "However, it has been shown that clinically-approved antibodies against EGFR or HER2 act predominantly through these immune mechanisms to reduce tumor growth." (PMID 37153618, 2023). "We can hypothesize that in these patients the tumor cells are strongly dependent from EGFR signalling activation." (PMID 37041632, 2023). "Another study revealed that IACS-13909, a potent and specific allosteric inhibitor of SHP2, effectively inhibited tumor cell proliferation in vitro and caused regression of tumors in vivo in NSCLC models that exhibited resistance to osimertinib due to EGFR mutations." (PMID 37662925, 2023). "Moreover, erlotinib combined with PPIs effectively inhibited tumor growth in xenografts, providing a new clinical option to overcome EGFR-TKI resistance in NSCLC." (PMID 37089959, 2023). "Dynamic changes in the tumor microenvironment are observed, particularly in responders, which may have implications for identifying predictive markers for EGFR-TKI treatment and guiding the future clinical trials." (PMID 37537219, 2023). "Nevertheless, data from this study indicate that dual targeting EGFR 20ins with JMT101 and osimertinib may bypass the limitations of TKIs and elicit tumor responses in a broader spectrum of 20ins variants." (PMID 37308490, 2023). "Although IgA is primarily known for its critical role as secretory IgA in mucous membrane immune functions, monomeric IgA antibodies have been successfully adapted to target tumor associated antigens such as HER2, EGFR, CD20, and GD2 in various in vitro and in vivo studies." (PMID 37444515, 2023). "EGFR mutant tumors are not very responsive to ICB therapy possibly due to their low tumor mutational burden (TMB) as compared to tumors carrying another common oncogenic driver of NSCLC, KRAS, which are more responsive to ICB." (PMID 37033953, 2023). "The immunosuppressive TME attenuates the efficacy of EGFR-TKIs in anti-tumor therapy." (PMID 37649478, 2023). "Interestingly, in none of the diverse cancer types analyzed, including TCGA Pan Cancer Atlas samples, we observed an increase of CBX3 transcripts compared to tumor samples which are diploid for either EGFR or RAC1." (PMID 37633946, 2023). "Human EGFR, Notch1, Notch2, and Notch3 mRNA were all expressed in tumours." (PMID 37441599, 2023). "Another reason is that the longer period of neoadjuvant EGFR-TKI might provide enough time for tumor to decrease." (PMID 36776292, 2023).
tumor (continued). "While tumors with wild-type RAS genes are highly sensitive to anti-EGFR therapy, erroneous administration of cetuximab or panitumumab to patients with RAS-mutated CRC may facilitate tumor growth." (PMID 36902296, 2023). "RVPNs decorated with a composite of an anti-EGFR single-domain antibody and iRGD provided long circulation time, improved extravasation and tumor localization, enhanced parenchymal penetration, as well as increased interaction with the overexpressed EGFR receptors." (PMID 36865093, 2023). "Furthermore, it has been reported that the microglia-GBM cells’ crosstalk modulates tumor infiltration by the activation of epidermal growth factor receptor (EGFR) and colony stimulating factor 1 receptor (CSF-1R) signaling." (PMID 37108208, 2023). "Moreover, siSTAT3 treatment attenuated the anti-tumor effects of siNOTCH4 treatment in EGFR-TKI-treated LUAD-PDX." (PMID 37268635, 2023). "Therefore, given tumor specificity and frequency, EGFR has been considered a compelling therapeutic target for GBM." (PMID 37537946, 2023). "Importantly, CD47‐SIRPα blockade with an anti‐CD47 antibody treatment significantly enhanced EGFR‐targeted cancer therapy and elicited much greater tumor growth inhibition than either treatment alone." (PMID 37541303, 2023). "The EGFR has also been linked to the development of HCC and CCA tumours in previous studies." (PMID 38414954, 2023). "Furthermore, αvβ3 also interacts with the epidermal growth factor receptor (EGFR) to regulate integrin binding to extracellular ligands required for vasculogenesis and tumor growth." (PMID 38213533, 2023). "Moreover, GPI-anchored proteins (associated with lipid rafts) were used to display a nanobody that targets epidermal growth factor receptor (EGFR), a well-studied oncogene, on the surface of EVs to target tumour cells expressing this receptor." (PMID 37189850, 2023). "Given the ubiquitous and abundant expression of EGFR in epithelial cells, it is important to account for potential toxicities that may arise from off-tumor targeting." (PMID 37545491, 2023). "Whether the tumor microenvironment including TAMs could play an important role in EGFR- and HER2-mediated cancer progression was also investigated." (PMID 36674955, 2023). "The different distribution of consensus molecular subtypes (CMS) between L- and R-sided tumors may explain the different sensitivity to anti-EGFR according to primary tumor site." (PMID 36895480, 2023). "However, results from the EVIDENCE trial showed that adjuvant icotinib significantly improves DFS in patients with EGFR-mutant stage II-IIIA NSCLC after complete tumor resection compared with adjuvant chemotherapy (47.0 vs. 22.1 months)." (PMID 36994198, 2023). "EGFR was overexpressed in TNBC and is associated with tumor growth and progression." (PMID 37174125, 2023). "To clarify the mechanism synergistic anti-cancer effect of FYLM, we investigated the protein expression of PRC1, Wnt pathway-related protein (β-catenin, c-Myc, c-Jun) and EGFR pathway-related protein (p-EGFR, EGFR, p-Akt and Akt) in xenograft tumor tissues by western blot and immunohistochemistry." (PMID 36744262, 2023). "The hypoxia-activated EGFR/HER2 inhibitor tarloxotinib, may be another mechanism of more specifically targeting EGFR or ERBB2 fusions in only tumor cells." (PMID 37168365, 2023). "For immune cell composition, activation of EGFR signaling could induce CCL2 expression and then elevate the infiltration of tumor-associated macrophages (TAMs) in the TME." (PMID 37759950, 2023). "Here, using our PDC models, we could directly assess EMT interference via EGFR-TKI resistance from spontaneous patient tumor clonal status." (PMID 36717865, 2023).
tumor (continued). "Hence, in our study we reported a novel role of DVL2 in oncogenic Wnt and EGFR signaling modulation as well as its promising correlation with markers of tumor immune regulation (such as TILs and cytotoxic CD8α)." (PMID 36809986, 2023). "On the other hand, many mutations in tumor tissue especially for EGFR (L858R) have not been detected in the plasma." (PMID 38041139, 2023). "While reducing immunosuppression through immune targeting and strengthening ICD, this combination also suppressed tumor proliferation by inhibiting tyrosine kinases (including EGFR signaling and RTK signaling) and effectively reduced drug resistance during the treatment process." (PMID 37584192, 2023). "EGFR may have a role in altering cellular phenotypes that promote tumor cell survival and proliferation." (PMID 37998363, 2023). "We hypothesized that imaging features extracted from pretreatment chest CT could improve the prediction of tumor progression after EGFR-TKI treatment in NSCLC patients." (PMID 36670497, 2023). "Similarly, RevCAR-E7B6 T cells were only able to induce significant tumor cell killing in the presence of the respective matching RevTMs (EGFR-7B6 and GD2-7B6)." (PMID 37122703, 2023). "The TP protein is cytotoxic to EGFR-expressing tumor cells in vitro and in xenograft mouse models." (PMID 36900277, 2023). "In addition to CD38, the epidermal growth factor receptor (EGFR) can also serve as a target for tumor cell-specific delivery of therapeutic nucleic acids." (PMID 38516300, 2023). "Furthermore, the study suggests that the upregulation of FUCA1 expression contributes to the repression of the EGFR signaling pathway and has tumor‐suppressing activity in various human cancers." (PMID 37601653, 2023). "Moreover, we observed a 20-fold induced expression of LIM homeobox domain 9, i.e. a putative tumor suppressor which was highly responsive to tobacco smoke exposure and determined 3-fold induced expression of epidermal growth factor to stimulate EGFR signaling." (PMID 37932771, 2023). "Interestingly, it has been found that eccDNA amplification in genes like EGFR, c-MYC, and RAB3B, which are associated with autophagy, can intensify the "stemness" of tumor cells." (PMID 39534571, 2023). "PAI, which reports the “binding potential” (BP, a value proportional to receptor concentration), has been used in a variety of EGFR-overexpressing xenograft cell lines to demonstrate that tumor-averaged binding potential scales linearly with EGFR both in vivo and ex vivo." (PMID 34651290, 2023). "Additionally, other research has discovered that inhibition of PI4K2A along with EGFR inhibition better inhibits EGFR‐dependent tumor growth." (PMID 35634680, 2023). "EGFR is also involved in prolactinoma development, promoting tumor growth and prolactin secretion." (PMID 37958474, 2023). "Moreover, SAgs were fused with the third loop of transforming growth factor α (TGFαL3) to study the possibility of the therapeutic application of TGFαL3-SAg as a novel anti-tumor candidate in EGFR tumor-expressing cells." (PMID 37445686, 2023). "However, EGFR-TKIs lead to acquired resistance and eventual tumor relapse, thereby affecting the patient survival and highlighting the urgent need to investigate novel strategies for circumventing drug resistance." (PMID 37920509, 2023). "For HER3, neither of the two included trials (the PICCOLO and CALGB 80203 trials) observed evidence for it as a prognostic biomarker but found tumor HER3 mRNA expression may be a useful predictive biomarker for anti-EGFR therapy in RAS wt patients." (PMID 37974093, 2023). "Interestingly, increased expression of lnc-EGFR was observed in HCC that was accompanied by an increased ratio of Treg cells within the tumor micro-environment." (PMID 37189549, 2023).